ITPR1 (inositol 1,4,5-trisphosphate receptor type 1)
Diseases named in the same sentence as ITPR1 in open-access papers (continued):
Sharing a sentence is not in itself a finding about the gene and the disease.
schizophrenia (2 papers, 2017 to 2023). A major psychotic disorder characterized by abnormalities in the perception or expression of reality. "Interestingly, a recent whole-exome sequencing (WES) study identified 11 individuals with schizophrenia who had ultra-rare disrupting/damaging variants in ITPR1." (PMID 29187259, 2017). "We also identified a novel 280 kb deletion at 3p26.1 overlapping schizophrenia candidate genes ITPR1 and SUMF1 that has not been previously reported in the literature." (PMID 29187259, 2017). "We also identified a novel 280-kb deletion at 3p26.1 overlapping genes SUMF1 and ITPR1 in a participant with schizophrenia-NVLD that has not been previously reported in the literature." (PMID 29187259, 2017).
steatosis (2 papers, 2021 to 2022). Increased lipid within the cytoplasm of cells. "ITPR1 and ITPR2 may thus promote senescence and subsequent key drivers of age-related defects in the liver, including steatosis and alterations of glucose homeostasis." (PMID 33526781, 2021).
Stroke (2 papers, 2016 to 2022). Sudden impairment of blood flow to a part of the brain due to occlusion or rupture of an artery to the brain. "Notably, repeated stroke episodes attributed to intermittent atrial fibrillation occurred in one patient with ITPR1-IgG/anti-Sj-associated dysautonomia." (PMID 35907972, 2022).
thyroid cancer (2 papers, 2015 to 2022). "In conclusion, we developed a novel seven-mRNA (CDKN2A, FGF7, CTSB, HAP1, DAPK2, DNAJB1, ITPR1) risk model and nomogram that could help assess the prognosis of patients and guide clinical decision-making and individualized therapy for differentiated thyroid cancer." (PMID 35459137, 2022). "The results showed that ITPR1 was highly expressed in both FTC-133 and TPC-1 thyroid cancer cell lines, and the hazard ratio of ITPR1 indicated that ITPR1 was an oncogene, and showed research potential of its biological mechanism." (PMID 35459137, 2022). "Downregulation of ITPR1 has been demonstrated in thyroid cancer in comparison to non-malignant thyroid tissue in a number of studies." (PMID 25922907, 2015).
amnesia (1 paper, 2022). Pathologic partial or complete loss of the ability to recall past experiences ( AMNESIA, RETROGRADE) or to form new memories ( AMNESIA, ANTEROGRADE). "Very recently, a patient with suspected ITPR1-IgG seropositivity and confabulations, amnesia, and motor memory loss has been reported." (PMID 35907972, 2022).
Atrophy (1 paper, 2015). Any weakening or degeneration, especially through lack of use. "The difficulty of resolving the apparent contradiction between a clinically stable disorder with cerebellar imaging suggestive of atrophy is also illustrated in the case of ITPR1 mutations where there do not appear to be consistent genotype–imaging correlations." (PMID 25981959, 2015).
auriculocondylar syndrome (1 paper, 2021). Auriculo-condylar syndrome (ACS) presents with bilateral external ear malformations ('question mark' ears), mandibular condyle hypoplasia, microstomia, micrognathia, microglossia and facial asymmetry. "PLCB4, EDN, and EDNRA are closely related to human auriculocondylar syndrome (ACS, MIM #614669, #602483, #615706), which shares similar phenotypes with OAVS like ear and mandibular deformities, suggesting a functional link with ITPR1." (PMID 33747042, 2021).
autoimmune disease (1 paper, 2018). A disorder resulting from loss of function or tissue destruction of an organ or multiple organs, arising from humoral or cellular immune responses of the individual to their own tissue constituents. "Overexpression of ITPR1 gene results in calcium dysregulation accentuating the risk of autoimmune diseases." (PMID 29503661, 2018).
cancer of the larynx (1 paper, 2016). "The selection of the validated ITPR1 gene (inositol 1,4,5-trisphosphate receptor, type 1) can contribute significantly to the understanding of processes including cancer of the larynx since it has functions related to apoptosis, tumorigenesis of cells squamous and cell proliferation." (PMID 27209356, 2016).
developmental delay (1 paper, 2023). "To our surprise, we found a heterozygous variant ITPR1:NM_001378452.1:c.7660 G > A;p.(Gly2554Arg) in both affected sisters (explaining the global developmental delay phenotype) which was absent in the parents strongly suggesting a gonadal mosaic mode of inheritance." (PMID 37644014, 2023).
dysautonomia (1 paper, 2022). An acute or chronic disorder, affecting the sympathetic or parasympathetic nervous system. "Overall, dysautonomia has been reported in 4/19 (21%) ITPR1-IgG/anti-Sj-seropositive patients." (PMID 35907972, 2022). "Studies evaluating the frequency of ITPR1-IgG/anti-Sj in patients with paraneoplastic or non-paraneoplastic autonomic enteropathy and other types of dysautonomia may thus be warranted." (PMID 35907972, 2022).
endometrial cancer (1 paper, 2020). Primary or metastatic malignant neoplasm involving the endometrium (mucous membrane that lines the endometrial cavity). "The estrogen signaling pathway, which is highly associated with the development of endometrial cancer, showed enrichment of four differentially expressed ARGs (ITPR1, FOS, PRKCD, and BCL2)." (PMID 33109128, 2020).
Epileptic encephalopathy (1 paper, 2020). A condition in which epileptiform abnormalities are believed to contribute to the progressive disturbance in cerebral function. "ZDHHC9, ITPR1, and GLRA1 showed meaningful variants in the gene panel for neurodevelopment disorders during reanalysis but were not actually included in the gene panel for epileptic encephalopathy." (PMID 32695065, 2020).
esophageal cancer (1 paper, 2022). A primary or metastatic malignant neoplasm involving the esophagus. "ITPR1 is down-regulated in head and neck tumors and esophageal cancer." (PMID 35313846, 2022). "As an autophagy gene, ITPR1 was down-regulated in head and neck tumor and esophageal cancer." (PMID 35313846, 2022).
fetal growth restriction (1 paper, 2020). A fetus that does not grow beyond the 10th percentile of conventionally accepted weight for gestational age. "Therefore, we hypothesized that decreased expression of ITPR1 in placenta may lead to accelerated aging of the tissue, an early tissue senescence that increases the risk of adverse fetal outcomes including fetal growth restriction and low birthweight." (PMID 32407400, 2020).
Friedreich ataxia (1 paper, 2015). An inherited condition that affects the nervous system and causes movement problems. "Triplet repeat copy number in Friedreich ataxia patients has been reported to range between 66 and 1,700 subunits, thus the GAA repeat expansion observed in canine ITPR1 falls within this range." (PMID 25354648, 2015).
Infertility (1 paper, 2023). "Because of the known involvement of ITPR1 in cellular calcium influx and its association with the progression of infertility in NOA patients, the level of Ca2+ as well as other clinicopathological factors related to infertility including FSH, LH, TT, and Vit." (PMID 38072953, 2023). "Moreover, the positive correlation of increased expression of the ITPR1 gene with increased levels of serum calcium in NOA patients could confirm the association of ITPR1 gene expression with infertility through Ca2+ influx/apoptosis pathway crosstalk." (PMID 38072953, 2023).
Iris hypoplasia (1 paper, 2016). "Iris hypoplasia is likely to result from either complete loss of ITPR1 activity or structure-specific disruption of multimeric interactions." (PMID 27108798, 2016).
Jacobsen syndrome (1 paper, 2024). A multiple congenital anomaly/intellectual disability contiguous gene syndrome caused by partial deletion of the long arm of chromosome 11. "Most importantly, the use of WES has allowed us to both assess variants in known ASD genes (i.e., CYP1B1, ITPR1, MAB21L1, PXDN, and PITX2) and to identify rarer phenotypes (i.e., MIDAS, oculogastrointestinal-neurodevelopmental syndrome and Jacobsen syndrome)." (PMID 38459225, 2024).
kidney cancer (1 paper, 2022). Primary or metastatic malignant neoplasm involving the kidney. "ITPR1 participated in autophagy induced by NK cells and reduced the killing effect of cytokines secreted by NK cells on kidney cancer." (PMID 35313846, 2022). "In kidney cancer, HIF2α affected the expression of ITPR1 and activated autophagy of target cells through NK-derived signals, thereby regulating NK-mediated killing." (PMID 35313846, 2022). "ITPR1 was a new target of HIF-2α, which protected kidney cancer cells from NK-mediated lysis by inducing NK-mediated autophagy." (PMID 35313846, 2022).
malaria (1 paper, 2025). Malaria is a serious and sometimes fatal disease caused by a parasite that commonly infects a certain type of mosquito which feeds on humans. "The upregulation of CAMK2A and ITPR1 in Ml during malaria reflects an active calcium-mediated immune response that promotes T cell activation, gene transcription, and inflammatory signaling to support effective host defense." (PMID 41333726, 2025).
multiple sclerosis (1 paper, 2023). A progressive autoimmune disorder affecting the central nervous system resulting in demyelination. "Furthermore, 59 sera of patients with multiple sclerosis and 50 sera of patients positive for different anti-neuronal autoantibodies (10 × anti-Yo, 10 × anti-Ri, 10 × anti-GAD65, 10 × anti-ITPR1, 10 × Sez6l2) were analyzed using RC-IIFA with HEK293-septin-3/5/6/7/11 complex cells as controls." (PMID 36997937, 2023).
neurotoxicity (1 paper, 2022). Toxicity that causes injury to the central or peripheral nervous system or damages its function. "The third module included 3 genes in Neurotoxicity (Itpr1, Trim8, Lrp1), 4 in Blood–brain barrier (Ptpn23, Claudin5, Plectin, Mmp2) and 4 in Cognitive function (Slc8a3, Srf, Nf1, Ncam1)." (PMID 35899365, 2022).
ovarian endometriosis (1 paper, 2022). A non-neoplastic disorder characterized by the growth of endometrial tissue in the ovaries. "ITPR1 was also elevated in ovarian endometriosis tissues than normal." (PMID 35580861, 2022).
Sjögren's syndrome (1 paper, 2025). "While a connection to Sjögren's syndrome cannot be excluded, the role of ITPR1 as the primary cause remains the focus." (PMID 41325768, 2025). "While a potential association with Sjögren's syndrome was considered, the genetic finding suggests a distinct cause, warranting further exploration of ITPR1 variants in undiagnosed SAN cases." (PMID 41325768, 2025).
spinocerebellar ataxia type 26 (1 paper, 2017). Spinocerebellar ataxia type 26 (SCA26) is a very rare subtype of autosomal dominant cerebellar ataxia type III (ADCA type III) characterized by late-onset and slowly progressive cerebellar signs (gait ataxia) and eye movement abnormalities. "Mutations in Eef2 and Itpr1 cause spinocerebellar ataxia type 26 and 15/29, respectively." (PMID 28893375, 2017).
Spinocerebellar ataxia type 3 (1 paper, 2009). "Interestingly, mutant ataxin-3, which is the protein product of the gene mutated in spinocerebellar ataxia type 3 (SCA3), was shown to bind to ITPR1 and thereby cause a destabilization of neuronal calcium signaling." (PMID 19461874, 2009).
status epilepticus (1 paper, 2022). Status epilepticus is defined as a continuous seizure lasting more than 30 min, or two or more seizures without full recovery of consciousness between any of them. "One patient with high-titre ITPR1-IgG serum antibodies developed a status epilepticus; in a further high-titre patient (positive in both serum and CSF), “EEG-electrographic seizures” were documented." (PMID 35907972, 2022).
triple-negative breast carcinoma (1 paper, 2022). An invasive breast carcinoma which is negative for expression of estrogen receptor (ER), progesterone receptor (PR), and human epidermal growth factor receptor 2 (HER2). "Combined with our analysis, ITPR1 is correlated with the level of immune infiltration in triple-negative breast cancer, and is highly expressed in chemotherapy." (PMID 35313846, 2022). "And the correlation between the expression of ITPR1 and immune cell marker genes also suggests that ITPR1 might play a role in the immune regulation of triple-negative breast cancer." (PMID 35313846, 2022). "It suggests that the increase of ITPR1 may improve the sensitivity of immunotherapy combined with chemotherapy in the treatment of triple-negative breast cancer." (PMID 35313846, 2022). "The results showed that ITPR1 is related to monocytes, M2 macrophages, TAM, Th1 cells, neutrophils and dendritic cells of triple-negative breast cancer." (PMID 35313846, 2022). "Next, continue to analyze the correlation between the expression level of ITPR1 and clinical variables, and found that the expression of ITPR1 was related to hormone receptor-positive breast cancer, HER-positive breast cancer and triple-negative breast cancer." (PMID 35313846, 2022).
Type 1 Diabetes (1 paper, 2024). "We found GWAS links between 7 T2D-DMP genes and T2D or related phenotypes, including SPRED2 (T2D), ITPR1 and PLD6 (Diabetic complications), SLC16A3 (BMI), TCF7 (Type 1 Diabetes), RGL3 (blood pressure) and TNIP1 (autoimmune traits)." (PMID 38574408, 2024).
vitiligo (1 paper, 2022). Generalized well circumscribed patches of leukoderma that are generally distributed over symmetric body locations and is due to autoimmune destruction of melanocytes. "Additionally, disease activity and severity-based analyses revealed significantly decreased GZMB (p = 0.019 and 0.034), SERPINB9 (p = 0.031 and p = 0.035), and ITPR1 (p = 0.0003 and p = 0.034) transcripts in active vitiligo and severe GV patients' Tregs." (PMID 36157881, 2022).
cancer (42 papers, 2011 to 2025). A tumor composed of atypical neoplastic, often pleomorphic cells that invade other tissues. "The ITPR1 variant could be altering the inflammatory and immune response involved in the pathogenesis of conditions such as cancer since this function is enriched in the MetaScape analysis by this and other candidate genes (FOXM1, CACNA2D1 and NTRK1)." (PMID 37175550, 2023). "According to the updated criteria for PNS, ITPR1-IgG/anti-Sj could be classified as “intermediate-risk antibody (associated with cancer in 30–70%)”." (PMID 35907972, 2022). "In five of the 11 patients (45%), ITPR1-IgG/anti-Sj was associated with cancer." (PMID 35907972, 2022). "In addition to the functional association with oxytocin-related pathways, ITPR1 has a regulatory role on autophagy and sensitivity to chemotherapeutic agents in cancer cells." (PMID 33742056, 2021). "Therefore, EGOT/ITPR1 expression is associated with a favorable prognosis and enhances paclitaxel sensitivity in human cancer." (PMID 30999914, 2019). "Previous study also shows that upregulation of ITPR1 expression enhances autophagy, thereby sensitizes paclitaxel cytotoxicity, suggesting a favorable prognosis in human cancer." (PMID 39104385, 2024). "Meanwhile, it has been reported that lncRNA EGOT sensitizes paclitaxel cytotoxicity via enhancing autophagy by upregulating ITPR1 expression in cancer cells." (PMID 38006396, 2023). "Recently, induced by lncRNA EGOT, up-regulation of ITPR1 expression was also found can sensitize cancer cells to paclitaxel toxicity." (PMID 35580861, 2022). "In order to explored the expression of ITPR1 and its unique prognosis, the Oncomine database was first used to detect the expression of ITPR1 in 20 kinds of common cancers." (PMID 35313846, 2022). "ITPR1 has been shown to regulate autophagy and the sensitivity of cancer cells to chemotherapeutic drugs." (PMID 36090248, 2022). "Great functions have now ITPR1 be proved; more investigations are still required to evaluate its diverse functions in multiply cancers." (PMID 35580861, 2022). "EGOT-triggered pre-ITPR1 AS contributes to the expression of the ITPR1 protein, which sensitizes cells to paclitaxel in cancer therapy." (PMID 35427215, 2022). "The results showed that compared with normal tissues, the expression of ITPR1 in cancer tissues was significantly reduced." (PMID 35313846, 2022). "Previously, ITPR1 has been reported to promote autophagy and thus sensitize paclitaxel cytotoxicity in human cancers." (PMID 34378314, 2021). "ITPR1 has been reported to be involved in Ai-lncRNA EGOT-mediated paclitaxel resistance in human cancers." (PMID 34621314, 2021). "The eosinophil granule ontogeny transcript (lncRNA EGOT) recruits heterogeneous nuclear ribonucleoprotein H1 (hnRNPH1) to enhance the alternative splicing of pre-inositol 1,4,5-trisphosphate receptor type 1 (ITPR1) to promote autophagy in human cancer." (PMID 32429086, 2020). "Overall, we provide compelling evidence that in response to stress, EGOT activates autophagy via ITPR1, which sensitizes paclitaxel cytotoxicity in human cancer." (PMID 30999914, 2019). "Taken together, these data indicate the pivotal roles of EGOT fragment 2 (324–645 nucleotides) in exon 1, which binds to pre-ITPR1 to control ITPR1 expression in cis in human cancer." (PMID 30999914, 2019). "The result was validated by experimental evidence showing that ITPR1 knockdown conferred protection to cancer cells from paclitaxel." (PMID 30999914, 2019). "In PTC, ITPR1 expression has been found to be upregulated, suggesting that it may contribute to the dysregulation of calcium signaling pathways in this cancer." (PMID 37056339, 2023). "The TIMER database studied the relationship between ITPR1 and cancer immune infiltration." (PMID 35313846, 2022).